RRP1 (ribosomal RNA processing 1)
Description:
Plays a critical role in the generation of 28S rRNA.
Synonyms: NNP-1; D21S2056E; NOP52; RRP1A
Tractability: Small molecule: a structure with a bound ligand is known. PROTAC: ubiquitination databases record sites on it; its protein half-life has been measured.
Gene: Protein-coding gene on chromosome 21 (43,789,513 to 43,805,757, forward strand). Ensembl gene ENSG00000160214.
Subcellular location: Nucleus, nucleolus
Subcellular location (Human Protein Atlas): Mitotic chromosome; Nucleoli
Pathways (Reactome):
Metabolism of RNA: Major pathway of rRNA processing in the nucleolus and cytosol
Gene Ontology:
Molecular function: protein binding; RNA binding; transcription coactivator activity
Biological process: regulation of transcription by RNA polymerase II; positive regulation of DNA-templated transcription; rRNA processing
Cellular component: chromosome; nucleolus; nucleus; preribosome, small subunit precursor
Genetic constraint (gnomAD): Loss-of-function variants: 37 observed, 54.29 expected, observed/expected ratio (o/e) 0.68, 90% interval 0.52 to 0.9. The upper end of that interval is the gene's LOEUF score, 0.9, which puts it in group 3 of 6, group 1 being the genes least tolerant of losing a copy. Missense variants: 639 observed, 592.27 expected, observed/expected ratio (o/e) 1.08, 90% interval 1.01 to 1.15. Synonymous variants: 262 observed, 236.52 expected, observed/expected ratio (o/e) 1.11, 90% interval 1 to 1.23.
Homologues: Orthologues: chimpanzee RRP1 (99% identical), macaque RRP1 (83% identical), pig RRP1 (69% identical), dog RRP1 (69% identical), rat Rrp1 (66% identical), guinea pig RRP1 (66% identical), mouse Rrp1 (65% identical), tropical clawed frog rrp1b (42% identical), zebrafish rrp1 (38% identical), Drosophila melanogaster Nnp-1 (25% identical), Caenorhabditis elegans rrp-1 (21% identical). Paralogues in human: RRP1B (45% identical).
Diseases named in the same sentence as RRP1 in open-access papers:
RRP1 is named in the same sentence as 6 diseases in open-access papers, as found by Europe PMC text mining. Sharing a sentence is not in itself a finding about the gene and the disease. The quoted sentences say what the papers report.
lung adenocarcinoma (2 papers, 2023 to 2025). A carcinoma that arises from the lung and is characterized by the presence of malignant glandular epithelial cells. "The expression of ADI1 and RRP1 could be used to monitor the correct inhibition of HSP90 in lung adenocarcinoma." (PMID 37762133, 2023).
endometriosis (1 paper, 2025). The growth of functional endometrial tissue in anatomic sites outside the uterine body. "The four hypomethylated genes in endometriosis are RRP1, DIPC2, USP1, and DNMT1." (PMID 39858463, 2025). "The p-values indicate that four genes (DIP2C, DNMT1, RRP1, and USP1) are significantly differentially hypomethylated in the endometriosis group compared to the control group." (PMID 39858463, 2025).
lung carcinoma (1 paper, 2023). "Consistent with this, lower RRP1 expression correlates with improved disease progression outcomes and overall survival in lung cancer." (PMID 37762133, 2023).
infection (4 papers, 2011 to 2024). The state of being infected such as from the introduction of a foreign agent such as serum, vaccine, antigenic substance or organism. "We show that Rrp1 is dispensable for mammalian infection but is essential for spirochetal survival in the tick vector." (PMID 21738477, 2011). "The Hk1/Rrp1 two-component system, which promotes tick-adaptation during feeding but is not required for mammalian infection, is a candidate counter-regulatory pathway." (PMID 22359504, 2012). "In this study, we show that Rrp1, the only diguanylate cyclase in B. burgdorferi, is not required for mammalian infection but is essential for spirochete survival in the tick vector." (PMID 21738477, 2011). "Work on Rrp1 from this study and previous studies strongly supports the notion that c-di-GMP is essential for spirochetal adaptation in the tick vector but is not required for mammalian infection." (PMID 21738477, 2011).
cancer (1 paper, 2025). A tumor composed of atypical neoplastic, often pleomorphic cells that invade other tissues. "Based on the transcriptomic data of TCGA pan-cancer cohorts, the expression of RRP1B, RRP1, MAZ, DUS1L, and HGH1 was identified to correlate positively with the expression of SLC19A1 in 40 types of cancers." (PMID 40149548, 2025).
RRP1 also shares sentences with these, for which no sentence is quoted: spirochetal infection (1 paper).